OPRL1 (opioid related nociceptin receptor 1)
Description:
G protein-coupled opioid receptor that functions as a receptor for the endogenous neuropeptide nociceptin. Ligand binding causes a conformation change that triggers signaling via guanine nucleotide-binding proteins (G proteins) and modulates the activity of down-stream effectors. Signaling via G proteins mediates inhibition of adenylate cyclase activity and calcium channel activity. Arrestins modulate signaling via G proteins and mediate the activation of alternative signaling pathways that lead to the activation of MAP kinases. Plays a role in modulating nociception and the perception of pain. Plays a role in the regulation of locomotor activity by the neuropeptide nociceptin.
Synonyms: KOR-3; OOR; ORL1; NOCIR; NOPr; PNOCR; KOR3; NOP; OPRL
Tractability: Small molecule: a drug acting on it is in phase 2 or 3 trials; a structure with a bound ligand is known; a high-quality ligand is known; it belongs to a druggable protein family. Antibody: its Gene Ontology location is reachable by antibodies, with high confidence; UniProt places it where antibodies can reach, with medium confidence; UniProt predicts a signal peptide or a membrane-spanning region. PROTAC: a small molecule that binds it is known.
Target class: Short peptide receptor (family A GPCR); Family A G protein-coupled receptor; Peptide receptor (family A GPCR); Opioid receptor; Membrane receptor
Chemical probes: SB-612111 (high quality)
Safety:
Unwanted effects reported when the protein is acted on. In parentheses: how it was acted on, where the effect was seen, and who reports it.
opioid dependence (source: ClinPGx)
Gene: Protein-coding gene on chromosome 20 (64,079,967 to 64,100,649, forward strand). Ensembl gene ENSG00000125510.
Subcellular location: Cell membrane; Cytoplasmic vesicle
Subcellular location (Human Protein Atlas): Primary cilium; Primary cilium tip
Pathways (Reactome):
Signal Transduction: G alpha (i) signalling events; Peptide ligand-binding receptors
Gene Ontology:
Molecular function: G protein-coupled receptor activity; nociceptin receptor activity; protein binding; neuropeptide binding; G protein-coupled opioid receptor activity; G protein-coupled peptide receptor activity
Biological process: adenylate cyclase-inhibiting G protein-coupled receptor signaling pathway; calcium-mediated signaling; phospholipase C-activating G protein-coupled receptor signaling pathway; neuropeptide signaling pathway; sensory perception; sensory perception of pain; G protein-coupled opioid receptor signaling pathway; G protein-coupled receptor signaling pathway; neuron-neuron synaptic transmission
Cellular component: plasma membrane; neuron projection; cytoplasmic vesicle; membrane; synaptic membrane
Genetic constraint (gnomAD): Loss-of-function variants: 9 observed, 21.88 expected, observed/expected ratio (o/e) 0.41, 90% interval 0.25 to 0.72. The upper end of that interval is the gene's LOEUF score, 0.72, which puts it in group 2 of 6, group 1 being the genes least tolerant of losing a copy. Missense variants: 406 observed, 535.93 expected, observed/expected ratio (o/e) 0.76, 90% interval 0.7 to 0.82. Synonymous variants: 223 observed, 241.75 expected, observed/expected ratio (o/e) 0.92, 90% interval 0.83 to 1.03.
Homologues: Orthologues: chimpanzee OPRL1 (98% identical), macaque OPRL1 (98% identical), guinea pig OPRL1 (95% identical), pig OPRL1 (94% identical), mouse Oprl1 (94% identical), rat Oprl1 (79% identical), tropical clawed frog oprl1 (67% identical), zebrafish oprl1 (59% identical), Caenorhabditis elegans trhr-1 (21% identical), Drosophila melanogaster Rh7 (18% identical). Paralogues in human: OPRK1 (52% identical), OPRD1 (51% identical), OPRM1 (50% identical), SSTR3 (36% identical), SSTR5 (35% identical), SSTR1 (35% identical), SSTR4 (35% identical), SSTR2 (32% identical), NPBWR2 (31% identical), NPBWR1 (31% identical), KISS1R (30% identical), CMKLR2 (26% identical), and 5 more.
Diseases named in the same sentence as OPRL1 in open-access papers:
OPRL1 is named in the same sentence as 50 diseases in open-access papers, as found by Europe PMC text mining. Sharing a sentence is not in itself a finding about the gene and the disease. The quoted sentences say what the papers report.
Anxiety (6 papers, 2013 to 2024). Intense feelings of nervousness, tension, or panic often arise in response to interpersonal stresses. "Zhang found that intraperitoneal injection of the OPRL1 antagonist JTC-801 reversed pain and anxiety caused by post-traumatic stress disorder (PTSD) in mice." (PMID 32111963, 2020).
alcohol use disorders (3 papers, 2016 to 2022). "The OPRL1 genotype has repeatedly been replicated on alcohol use disorders." (PMID 32601453, 2020). "Although there has been no study on the methylation of the OPRL1 gene body and gene expression in the human brain, this type of epigenetic modulation of the OPRL1 gene may contribute to the reduced OPRL1 mRNA observed in the postmortem brain of patients with alcohol use disorder." (PMID 36233105, 2022).
head and neck squamous cell carcinoma (2 papers, 2022 to 2025). A squamous cell carcinoma that arises from any of the following anatomic sites: lip and oral cavity, nasal cavity, paranasal sinuses, pharynx, larynx, and salivary glands. "We will investigate the mechanistic roles of N/OFQ and OPRL1 in head and neck squamous cell carcinoma (HNSCC) and melanoma patients and translate these findings into a mouse model." (PMID 40951290, 2025).
hepatocellular carcinoma (2 papers, 2022 to 2025). A malignant tumor that arises from hepatocytes. "Unbiased survival analysis indicates that high N/OFQ:OPRL1 activity correlates with better survival in HNSCC and skin cutaneous melanoma (SKCM) but may worsen outcomes in hepatocellular carcinoma." (PMID 40951290, 2025).
alcohol-dependent (1 paper, 2022). "Genome-wide methylation analysis of blood samples from monozygotic twins with or without alcohol dependence reveals a strong association of alcohol dependence with a differentially methylated site in the gene body of OPRL1." (PMID 36233105, 2022). "In a cohort of European Americans that were alcohol-dependent with or without childhood adversity, analysis of blood DNA methylation levels in the promoter regions of targeted genes further shows that the OPRL1 promoter is hypermethylated in patients regardless of childhood adversity experience." (PMID 36233105, 2022).
and neck tumors (1 paper, 2025). "Collectively, our findings indicate that melanoma and head and neck tumors are innervated by neurons upregulating Oprl1, and these tumors also harbor Pnoc-expressing B-cells." (PMID 40951290, 2025).
atherosclerosis (1 paper, 2025). A disease characterized by the build-up of fatty material and calcium deposition in the arterial wall resulting in partial or complete occlusion of the arterial lumen. "Six shared loci that were shared across all traits in the analysis, all with known associations with atherosclerosis (nearest genes: MAT2A, IRS1, STAG1, PVRL2, OPRL1, ARVCF)." (PMID 40313769, 2025).
ischemia (1 paper, 2025). A hypoperfusion of the BLOOD through an organ or tissue caused by a PATHOLOGIC CONSTRICTION or obstruction of its BLOOD VESSELS, or an absence of BLOOD CIRCULATION. "Namely, the peptide reduced the expression of many genes (e.g., P2rx6, Gabra3, Grik4, Oprl1, Glra2, Crhr1, Hrh1, Chrm5, Grik1) related to the neurosignaling system and whose expression was not significantly changed by ischemia itself." (PMID 40650034, 2025).
melanoma (1 paper, 2025). A malignant, usually aggressive tumor composed of atypical, neoplastic melanocytes. "We identified B cells as the primary source of N/OFQ and observed that high expression of either Pnoc or Oprl1 correlates with better survival in both melanoma and HNSCC." (PMID 40951290, 2025). "In a melanoma mouse model, tumor-innervating neurons also overexpressed Oprl1, and similar overexpression was observed when DRG neurons were co-cultured with B16F10 cells." (PMID 40951290, 2025). "We will also determine how N/OFQ:OPRL1 signaling affects tumor progression and immune responses in murine melanoma models." (PMID 40951290, 2025). "Compared with vehicle-treated mice, SB612111 further intensified thermal hypersensitivity, peaking on day 11 post-inoculation suggesting an active N/OFQ:OPRL1 signal ongoing during melanoma progression." (PMID 40951290, 2025). "Next, we investigated whether N/OFQ:Oprl1 signaling controls melanoma-induced pain." (PMID 40951290, 2025). "Orthotopic B16F10-OVA melanoma cells (2×105) were inoculated into the right hind paws of wild-type mice, which subsequently received daily intradermal injections of vehicle (50 μL) or the OPRL1 antagonist SB612111 (3 mM; 50 μL), starting one day post-inoculation." (PMID 40951290, 2025). "To ascertain if B cell infiltration mediates this N/OFQ:OPRL1 effect, we depleted B-cells with an anti-CD19 antibody in a B16F10 melanoma model." (PMID 40951290, 2025). "By analyzing our previously published datasets in silico, we discovered that naïve DRG neurons co-cultured with B16F10-mCherry-OVA melanoma cells and OVA-specific CD8+ T-cells exhibited elevated Oprl1 expression in cancer-exposed TRPV1+ neurons." (PMID 40951290, 2025). "We then tested whether additional activation of OPRL1 with recombinant N/OFQ (0.6 μg/kg; 50 μL) could alleviate melanoma-induced pain." (PMID 40951290, 2025).
oral squamous cell carcinoma (1 paper, 2025). "In a mouse model of oral squamous cell carcinoma (oSCC), we found that nociceptor neurons in tongue tumors overexpress Oprl1 and exhibit severe mechanical pain hypersensitivity." (PMID 40951290, 2025). "We hypothesized that B cell–derived N/OFQ might bind OPRL1 on tumor-innervating sensory neurons, thereby reducing nociception (i.e. pain signaling) in a mouse model of oral squamous cell carcinoma (oSCC), a subtype of HNSCC." (PMID 40951290, 2025).
renal carcinoma (1 paper, 2024). A carcinoma arising from the epithelium of the renal parenchyma or the renal pelvis. "TLR4, OPRL1, and OGFR opioid receptor genes have been reported to be associated with renal cancer progression." (PMID 38352696, 2024).
substance abuse (1 paper, 2021). The use of a drug for a reason other than which it was intended or in a manner or in quantities other than directed. "Some of us previously investigated involvement of eight genes in the opioid system (OPRD1, OPRK1, OPRL1, OPRM1, PDYN, PENK, PNOC, and POMC) and their potential effects on substance abuse." (PMID 34440333, 2021).
cancer (7 papers, 2018 to 2025). A tumor composed of atypical neoplastic, often pleomorphic cells that invade other tissues. "A genome-wide association study of 2057 European patients with advanced cancer receiving opioid treatment identified PCMTD2 and OPRL1 on chromosome 20 as associated with variations in the regulation of cancer pain intensity." (PMID 40579593, 2025). "By carefully calibrating N/OFQ administration, balanced coactivation of OPRL1 and mu opioid receptors is a strategy that warrants further exploration and refinement to manage cancer pain, thereby limiting opioid-associated side effects." (PMID 40951290, 2025). "Overall, these findings confirm that N/OFQ signaling through OPRL1 suppresses nociceptor activity while reshaping the tumor immune environment, offering a novel approach to managing both cancer pain and anti-tumor immunity." (PMID 40951290, 2025). "Activating OPRL1 reduced tumor size, enhanced cytotoxic T-cell infiltration, and relieved cancer-induced thermal hypersensitivity." (PMID 40951290, 2025). "Targeting the N/OFQ:OPRL1 pathway represents a promising therapeutic strategy for simultaneously alleviating cancer pain and impeding tumor progression." (PMID 40951290, 2025). "We showed that activating the N/OFQ:OPRL1 axis reduces cancer pain, whereas blocking it worsens pain." (PMID 40951290, 2025). "Regarding OPRL1, it belongs to the Aγ family of G protein-coupled receptors, which are involved in various diseases, including cancer." (PMID 36011316, 2022). "Targeting the N/OFQ:OPRL1 pathway could simultaneously alleviate cancer-related pain, inhibit tumor growth, and bolster immunosurveillance." (PMID 40951290, 2025). "Some genes comprising CRRS have been reported to involve the malignant phenotypes in different cancers, such as CRTC2, FBXL22, OPRL1, and PSMA4." (PMID 34862329, 2021). "Furthermore, cancer cells did not modify their Pnoc or Oprl1 expression in the absence of nociceptor neurons, indicating that N/OFQ signaling primarily regulates neuronal activity and, in turn, affects tumor–neuron communication and immune responses." (PMID 40951290, 2025).
tumor (4 papers, 2020 to 2025). "To investigate these questions, we focused on Nociceptin/Orphanin FQ (N/OFQ) and its receptor (OPRL1) to better understand their roles in tumor-associated pain." (PMID 40951290, 2025). "In contrast, depleting CD19+ B cells or blocking OPRL1 led to increased tumor growth, reduced CD8+ T-cell infiltration and cytotoxic potential, exacerbated pain, and elevated CGRP levels." (PMID 40951290, 2025). "In this study, we propose that endogenous, immune-mediated N/OFQ signaling in the TME suppresses nociceptor neuron activity through the OPRL1, thereby boosting anti-tumor immunity." (PMID 40951290, 2025). "Lastly, ipsilateral L3-L5 dorsal root ganglia (DRG), which contain neuronal cell bodies that innervate the hindpaw, from MOC2 tumor mice had 5-fold higher Oprl1 expression compared to the contralateral side." (PMID 40951290, 2025). "Differential gene expression analysis showed that Oprl1 was overexpressed in DRG neurons from tumor-bearing mice." (PMID 40951290, 2025). "Given the highly heterogeneous trigeminal innervation in the head and neck region, we performed retrograde labeling from the tongue before tumor cell inoculation and subsequently conducted single-cell PCR on labeled trigeminal neurons to assess Oprl1 expression in tongue-innervating sensory neurons." (PMID 40951290, 2025). "Since OPRL1 blockade increased tumor-induced pain and impaired anti-tumor immunity, we asked whether it also heightens intra-tumoral neuronal activity." (PMID 40951290, 2025). "In these B cell–depleted mice, OPRL1 antagonism (SB612111) no longer influenced tumor growth, nociceptive behavior, or CGRP levels, indicating that B-cells are crucial for the antinociceptive and anti-tumor effects of N/OFQ." (PMID 40951290, 2025). "In addition, OPRL1 can activate markers on the surface of T cells, enhance CD4+ T and CD8+ T-cell proliferation, and alter cytokine secretion, which is closely involved in tumor progression." (PMID 36011316, 2022). "In HNSCC, we found that although elevated OPRL1 expression did not confer a clear survival benefit, higher PNOC levels correlated with more favorable clinical outcomes and lower tumor grade." (PMID 40951290, 2025).
OPRL1 also shares sentences with these, for which no sentence is quoted: infection (6 papers); Sepsis (4); coronary artery disease (2); depression (2); glioblastoma (2); myocardial infarction (2); neuroblastoma (2); Parkinson disease (2); arthropathy (1); bladder pain syndrome (1); breast carcinoma (1); cardiac hypertrophy (1); cognitive deficits (1); colitis (1); colorectal cancer (1); diabetic neuropathy (1); drug dependence (1); endotoxemia (1); fibromyalgia (1); heart (1); hospital-acquired infections (1); insomnia (1); middle ear infection (1); Nociception (1); non-small cell lung carcinoma (1); osteosarcoma (1); pancreatic cancer (1); Parkinsonism (1); post-traumatic stress disorder (1); psoriasis (1).
A further 6 diseases each share a sentence with OPRL1 in 1 paper.